NFYB (nuclear transcription factor Y subunit beta)
Diseases named in the same sentence as NFYB in open-access papers:
NFYB is named in the same sentence as 48 diseases in open-access papers, as found by Europe PMC text mining. Sharing a sentence is not in itself a finding about the gene and the disease. The quoted sentences say what the papers report.
colorectal cancer (5 papers, 2010 to 2026). A primary or metastatic malignant neoplasm that affects the colon or rectum. "For example, NFYB was reported to induce the high expression of E2F1 in colorectal cancer and mediate oxaliplatin resistance." (PMID 34933446, 2021). "NFYB drives paclitaxel resistance in breast cancer and oxalipatin resistance in colorectal cancer." (PMID 34879849, 2021). "NFYB-mediated upregulation of E2F1 enhances CHK1 signaling, contributing to chemotherapy resistance in colorectal cancer." (PMID 41424847, 2026).
liver cancer (4 papers, 2014 to 2025). An epithelial or non-epithelial malignant neoplasm that arises from the liver. "It has been reported that NFYB is highly expressed in the head and neck squamous cell carcinoma, lung cancer, cervical cancer, and liver cancer, which is consistent with our analysis results." (PMID 36152055, 2022). "Eight modules are both CNV-TF regulated and CNV-gene enriched, and among these eight CNV-TFs, YY1, MZF1, DAND5, NFYB, ESR1 have been reported in liver cancer development and metastasis." (PMID 24897108, 2014).
prostate carcinoma (4 papers, 2014 to 2025). A carcinoma that arises from epithelial cells of the prostate gland. "In normal prostate samples, we found that the major transcription regulators of stemness genes were HOXB4, NFYB, and TFE3, which differed from those in prostate cancer." (PMID 33985534, 2021).
glioma (3 papers, 2020 to 2025). A benign or malignant brain and spinal cord tumor that arises from glial cells (astrocytes, oligodendrocytes, ependymal cells). "Oxidative phosphorylation pathway activity is elevated in both the Glioma and C5 subgroup, and NFYB is a key transcription factor for the C5 subgroup, suggesting its possible involvement in GBM proliferation and recurrence, and its close association with mitochondrial function." (PMID 38510250, 2024).
hepatocellular carcinoma (3 papers, 2022 to 2025). A malignant tumor that arises from hepatocytes. "Combining menin inhibition and NFYB knockout increases hepatocellular carcinoma cell death." (PMID 41296561, 2025). "The results showed that NFYB expression was significantly higher in Cholangiocarcinoma (CHOL), colon cancer, esophageal cancer, head and neck cancer, hepatocellular carcinoma, and gastric cancer than in adjacent normal tissues." (PMID 36152055, 2022).
osteosarcoma (3 papers, 2015 to 2025). A usually aggressive malignant bone-forming mesenchymal neoplasm, predominantly affecting adolescents and young adults. "This is intriguing in that the inducible E2F1 system used in this study comes from an osteosarcoma, indicating that the NFYB-dependent E2F1 transcriptional program defined here might be tissue-specific." (PMID 26039627, 2015).
sarcoma (3 papers, 2015 to 2024). A usually aggressive malignant neoplasm of the soft tissue or bone. "An Oncomine query with the E2F1/NFYB signature revealed sarcoma as the most significant cancer type in tumor versus normal analysis." (PMID 26039627, 2015). "In five independent sarcoma datasets, the E2F1/NFYB signature is significantly associated with signatures (concepts) consisting of genes that are overexpressed in cancer compared to normal tissue." (PMID 26039627, 2015). "The Oncomine analysis further indicated lower expression of the E2F1/NFYB signature in drug sensitive sarcoma cell lines compared with drug resistant lines in six independent datasets." (PMID 26039627, 2015). "Finally, our cancer vs normal analysis using a set of genes jointly induced by E2F1 and NFYB demonstrated most significant overexpression in sarcoma." (PMID 26039627, 2015). "Together with the data showing that NFYB is protective against E2F1-mediated apoptosis, these results suggest that the NFYB-dependent E2F1 transcriptional program we defined may be involved in the oncogenesis or maintenance of sarcomas." (PMID 26039627, 2015). "Furthermore, in silico analysis of this subset of co-regulated genes suggests that the NFYB-dependent E2F1 program is upregulated and linked with various types of sarcoma when compared to corresponding normal tissue." (PMID 26039627, 2015). "Further enhancing this idea is the fact that E2F1 target genes induced in an NFYB-independent manner do not show this association with sarcoma." (PMID 26039627, 2015). "Our results showing NFYB to be protective against E2F1 mediated apoptosis moreover suggest this NFYB/E2F1 regulated gene set may be involved in the development or survival of sarcoma cells." (PMID 26039627, 2015).
dermatomyositis (1 paper, 2022). Dermatomyositis (DM) is a type of idiopathic inflammatory myopathy characterized by evocative skin lesions and symmetrical proximal muscle weakness. "NFYB, GRN and MVP were diagnostically significant for both dermatomyositis and polymyositis in the dataset for inflammatory myopathy." (PMID 36203997, 2022). "In polymyostis and dermatomyositis, MVP and GRN expression levels were significantly higher, while NFYB levels were significantly lower." (PMID 36203997, 2022).
dysferlinopathy (1 paper, 2022). "Currently, it is unclear if NFYB contributes to dysferlinopathy progression and more studies are needed." (PMID 36203997, 2022). "Consistent with the two datasets, MVP, GRN, and ERP29 expression were significantly upregulated, and RNF128, NFYB, and KPNA3 were significantly downregulated in the dysferlinopathy patients compared with the controls." (PMID 36203997, 2022). "In both datasets, MVP, GRN, and ERP29 showed significantly higher expression levels, while RNF128, NFYB, and KPNA3 had significantly lower expression levels in dysferlinopathy than normal controls." (PMID 36203997, 2022).
intestinal gastric cancer (1 paper, 2022). "The previous analysis found that NFYB was highly expressed in gastric cancer tissues and was associated with prognostic risk factors of gastric cancer (high T stage, poor differentiation, and diffuse gastric cancer)." (PMID 36152055, 2022). "Hence, NFYB was associated with gastric cancer stromal cell reprogramming." (PMID 36152055, 2022). "Meanwhile, our analysis showed that the expression of NFYB was higher in diffuse gastric cancer than in intestinal gastric cancer." (PMID 36152055, 2022). "Our analysis showed that the expression of NFYB was positively correlated with the degree of CAFs infiltration in gastric cancer patients." (PMID 36152055, 2022). "Our results also showed that NFYB expression was correlated with diffuse gastric cancer and poor differentiation of gastric cancer cells." (PMID 36152055, 2022). "Meanwhile, the analysis showed that the expression of NFYB was higher in poorly differentiated GC tissues and higher in diffuse gastric cancer than in intestinal gastric cancer." (PMID 36152055, 2022). "The results showed that NFYB was significantly overexpressed in gastric cancer tissues compared with normal gastric tissues, which was consistent with the results of TIMER data." (PMID 36152055, 2022). "The results showed that the expression of NFYB was correlated with T stage, age of onset, histological grade, and laurun type of gastric cancer." (PMID 36152055, 2022). "We then analyzed the correlation between NFYB expression and clinicopathology of gastric cancer." (PMID 36152055, 2022). "The expression of NFYB in 21-40 year-old gastric cancer patients was significantly higher than that in older gastric cancer patients, suggesting that NFYB may play a role in the occurrence and development of early-onset gastric cancer." (PMID 36152055, 2022). "This suggested that the expression of NFYB may be related to the prognosis of gastric cancer patients." (PMID 36152055, 2022). "We found that high expression of NFYB may be a promising prognostic biomarker in patients with gastric cancer." (PMID 36152055, 2022). "NFYB is highly expressed in multiple tumors and promotes tumor invasion, metastasis, and drug resistance, but its role in the occurrence and development of gastric cancer remains unclear." (PMID 36152055, 2022). "Meanwhile, NFYB may be a marker molecule of early-onset gastric cancer." (PMID 36152055, 2022). "The results showed that high expression of NFYB was associated with poor OS and DFS but not with PFS in gastric cancer patients." (PMID 36152055, 2022). "The expression of NFYB in stage I gastric cancer was not significantly different from that in normal tissues, but it was significantly up-regulated in stage II, III, and IV GC tissues compared with normal and stage I GC tissues." (PMID 36152055, 2022).
ovarian tumor (1 paper, 2023). "In our study, we found the expression level of NFYB is decreased in ovarian tumor tissues compared with adjacent normal tissues and positive correlation with expression level of ABO gene." (PMID 36415180, 2023).
pancreatic adenocarcinoma (1 paper, 2020). "Using the GSE15471 and TCGA-Pancreatic adenocarcinoma (PAAD) datasets, we analyzed the clinical importance of TOP2A-associated genes (HDAC1, HDAC2, HMGB1, HMGB2, NFYA, NFYB, NFYC, and SP1)." (PMID 32977589, 2020).
thyroid cancer (1 paper, 2022). "Several transcription factors including E2F7, FOXM1, NFYB, and CREB3L1 were significantly associated with the OS of thyroid cancer patients and may be the main regulators of ATC progression." (PMID 36192735, 2022).
cancer (24 papers, 2013 to 2025). A tumor composed of atypical neoplastic, often pleomorphic cells that invade other tissues. "B-Myb associates with NFYB, and thus provokes a cascade of oncogenic gene expression profiles in cancers." (PMID 39309447, 2024). "Notably, B-Myb associates with NFYB, binds to target gene promoters, enhancers and super-enhancers, and provokes a cascade of oncogenic gene expression profiles in cancers." (PMID 39309447, 2024). "Nuclear transcription factor Y subunit beta and nuclear transcription factor Y subunit alpha genes were significantly associated with the upregulated genes in mice treated with the combination of cancer therapeutics and B. bre JCM92 (boosted group)." (PMID 33668827, 2021). "Similarly, abundant studies demonstrated that E2F4, STAT1, MYC, ERG, and NFYB may play an important role in the pathogenesis and progression of various cancers, including OSCC, and the underlying mechanism may be related to dysregulated lncRNA." (PMID 32923393, 2020). "NFYB KO has been previously shown to be essential for most cancer cell lines (DepMap24Q4), so separating the effect of protein loss and its inability to bind to chromatin was not possible." (PMID 41296561, 2025). "Altogether, our study provides insights into understanding the potential role of NFYB in CAFs and its use as potential anti-cancer targets." (PMID 36152055, 2022). "As the NFYB gene has previously been shown in DepMap24Q4 to be essential for most cancer cell lines, only a partial gene KO could be achieved in most of the tested cell lines." (PMID 41296561, 2025). "Our study also found that the C5 subgroup with high NFYB expression had the highest G2M score and a relatively higher proportion of rGBM, indicating that NFYB is highly associated with GBM proliferation and recurrence resistance, consistent with previous studies on NFYB in other cancers." (PMID 38510250, 2024). "In conclusion, NFYB is differentially expressed in a variety of cancers." (PMID 36152055, 2022). "Hence, we used TCGA, TIMER, Kaplan-Meier Plot, and UALCAN databases to analyze the expression of NFYB in pan-cancers and assess its clinical prognostic value." (PMID 36152055, 2022). "In addition, we also found significant positive correlations of gene expressions between FOXM1 and the NFY subunits (NFYA, NFYB or NFYC) in several cancer types." (PMID 32858881, 2020). "This suggests that NFYB may have different functions in different types of cancer." (PMID 36152055, 2022). "Injury-induced populations were highest for TFs related to cell proliferation, self-renewal, and cancer involving both intrinsic (E2F family, MYC, and ZFX) and extrinsic (HIF1a, EPAS1/HIF2a, NFYB, LEF1, GLI2, VDR, and SMAD1/3/5) pathways." (PMID 38905342, 2024). "We used the TIMER database to analyze TCGA’s pan-cancer RNA-SEQ expression data and explore the expression of NFYB in various tumors." (PMID 36152055, 2022). "The NFYB/E2F1 complex becomes connected with FOXO1/3 and is the factor of the FOXO- dependent signaling cascade, which is activated in the cells of different cancers." (PMID 28031533, 2017). "Our pan-cancer analyses confirmed frequent ZNF714 overexpression in multiple tumors, possibly due to regional amplification, promoter hypomethylation, and Nuclear Transcription Factor Y Subunit Beta (NFYB) signaling." (PMID 37958512, 2023). "In summary, when considered together with data showing NFYB as protective against E2F1-mediated apoptosis, this analysis suggests that the joint E2F1/NFYB transcriptional program may play a role in cancer resistance to chemotherapy." (PMID 26039627, 2015). "In light of the established roles of E2F and NFY in cancer phenotypes, we sought to determine whether the transcriptional program jointly controlled by E2F1 and NFYB might define unique cancer states." (PMID 26039627, 2015).
cancer (continued). "CNV-TFs TBP and NFYB targeted HSPA2, HSPA8 and HSPA1A respectively, three members of heat shock protein 70 which could inhibit apoptosis in cancer cells through simultaneous and independent mechanisms." (PMID 24897108, 2014).
tumor (13 papers, 2014 to 2026). "High NFYB expression was associated with GC stromal score, and about 50% of stromal cells in the tumor microenvironment were CAFs." (PMID 36152055, 2022). "More studies have shown that the high expression of NFYB is closely related to the elevation of tumor resistance to chemotherapeutic agents." (PMID 38510250, 2024). "NFYB was highly expressed in multiple tumors and promotes tumor invasion, metastasis, and drug resistance." (PMID 36152055, 2022). "The expression of FAP, α-SMA, and Vimentin was more strongly correlated with NFYB, and these markers were closely related to tumor invasion and metastasis." (PMID 36152055, 2022). "Moreover, transcription factor activity analysis revealed elevated activity of several transcription factors, such as ARID2, E2F1, E2F4, NFYB, and MYC, in the RRhighepi group, all of which are closely associated with cell proliferation and tumor progression." (PMID 41424847, 2026). "Furthermore, TFE3, TFDP1, NFYB, and RB1, associated with the cell cycle and apoptosis, were inferred in FSTL1+ tumor cells." (PMID 37430270, 2023). "However, it has been reported that NFYB can promote T cell infiltration in the tumor microenvironment." (PMID 36152055, 2022). "To validate the essential role of CREB3L1, E2F7, FOXM1, and NFYB in ATC progression, we detected their gene expression levels in both human tumor tissues and cell lines." (PMID 31183379, 2019). "We speculate that macrophage M1 and M0 may regulate tumor invasion and dividing ability in a non-directional manner and may pass through certain pathways of the transcription factor NFYB in order to fulfill related functions and interconvert each other." (PMID 38510250, 2024). "Therefore, NFYB may not promote tumor development through the immunosuppressive effect of CAFs." (PMID 36152055, 2022).
infection (11 papers, 2010 to 2025). The state of being infected such as from the introduction of a foreign agent such as serum, vaccine, antigenic substance or organism. "Our findings showed that the downregulation of genes controlled by the transcription factors NFYA/NFYB, ZBTB7A, and PBX3 was a common feature of cells susceptible to infection both before and after exposure." (PMID 40725231, 2025). "We also discovered that WT infection led to more nuclear localized NFYB (nuclear transcription factor Y subunit beta)." (PMID 29207503, 2017). "At 20°C, the expression of Ciita, NFYB, NFYC, CALR, Canx and TNF reached the peak at 24 hpi, which was significantly higher and earlier compared to 10°C infection group." (PMID 35197977, 2022). "In infection-susceptible cells, genes regulated by the transcription factors NFYA/NFYB, ZBTB7A, and PBX3 were downregulated both in the presence and absence of infection." (PMID 40725231, 2025).
inflammatory myopathy (1 paper, 2022). "In inflammatory myopathies, GRN, MVP and NFYB showed high diagnostic value, while RNF128, ERP29 and KPNA3 showed poor diagnostic value, indicating high inflammation activation but little involvement of protein homeostasis." (PMID 36203997, 2022).
NFYB also shares sentences with these, for which no sentence is quoted: breast carcinoma (3 papers); colon cancer (2); diffuse large B-cell lymphoma (2); lung carcinoma (2); acute myeloid leukemia (1); alcoholism (1); alveolar rhabdomyosarcoma (1); autism (1); brucellosis (1); Brugada syndrome (1); cervical cancer (1); cervical squamous cell carcinoma (1); cholangiocarcinoma (1); coronary atherosclerosis (1); cyclosporiasis (1); endocervical adenocarcinoma (1); endometriosis (1); esophageal cancer (1); follicular lymphoma (1); glioblastoma (1); head and neck cancer (1); head and neck squamous cell carcinoma (1); leukemia (1); lung squamous cell carcinomas (1); malaria (1); myeloid leukemia (1); polymyositis (1); schistosomiasis (1); skin cutaneous melanoma (1); testicular cancer (1).
A further 1 disease shares a sentence with NFYB in 1 paper.